KLHL12 (kelch like family member 12)
Description:
Substrate-specific adapter of a BCR (BTB-CUL3-RBX1) E3 ubiquitin ligase complex that acts as a negative regulator of Wnt signaling pathway and ER-Golgi transport. The BCR(KLHL12) complex is involved in ER-Golgi transport by regulating the size of COPII coats, thereby playing a key role in collagen export, which is required for embryonic stem (ES) cells division: BCR(KLHL12) acts by mediating monoubiquitination of SEC31 (SEC31A or SEC31B). The BCR(KLHL12) complex is also involved in neural crest specification: in response to cytosolic calcium increase, interacts with the heterodimer formed with PEF1 and PDCD6/ALG-2, leading to bridge together the BCR(KLHL12) complex and SEC31 (SEC31A or SEC31B), promoting monoubiquitination of SEC31 and subsequent collagen export. As part of the BCR(KLHL12) complex, also acts as a negative regulator of the Wnt signaling pathway by mediating ubiquitination and subsequent proteolysis of DVL3. The BCR(KLHL12) complex also mediates polyubiquitination of DRD4 and PEF1, without leading to degradation of these proteins.
Synonyms: C3IP1; DKIR
Tractability: Small molecule: it has a binding pocket of medium quality; it belongs to a druggable protein family. PROTAC: UniProt records ubiquitination sites on it; ubiquitination databases record sites on it.
Gene: Protein-coding gene on chromosome 1 (202,891,096 to 202,928,636, reverse strand). Ensembl gene ENSG00000117153.
Subcellular location: Cytoplasmic vesicle, COPII-coated vesicle
Subcellular location (Human Protein Atlas): Centriolar satellite; Vesicles
Pathways (Reactome):
Signal Transduction: Degradation of DVL
Gene Ontology:
Molecular function: identical protein binding; protein binding; ubiquitin-like ligase-substrate adaptor activity
Biological process: COPII vesicle coating; endoplasmic reticulum to Golgi vesicle-mediated transport; neural crest cell development; neural crest formation; protein monoubiquitination; Wnt signaling pathway; proteasome-mediated ubiquitin-dependent protein catabolic process; anatomical structure morphogenesis; protein ubiquitination; tissue development
Cellular component: COPII vesicle coat; COPII-coated ER to Golgi transport vesicle; Cul3-RING ubiquitin ligase complex; cytoplasm; cytosol
Genetic constraint (gnomAD): Loss-of-function variants: 15 observed, 53.05 expected, observed/expected ratio (o/e) 0.28, 90% interval 0.19 to 0.44. The upper end of that interval is the gene's LOEUF score, 0.44, which puts it in group 1 of 6, group 1 being the genes least tolerant of losing a copy. Missense variants: 419 observed, 679.91 expected, observed/expected ratio (o/e) 0.62, 90% interval 0.57 to 0.67. Synonymous variants: 202 observed, 240.05 expected, observed/expected ratio (o/e) 0.84, 90% interval 0.75 to 0.95.
Homologues: Orthologues: chimpanzee KLHL12 (100% identical), macaque KLHL12 (100% identical), guinea pig KLHL12 (99% identical), rat Klhl12 (99% identical), mouse Klhl12 (99% identical), rabbit KLHL12 (99% identical), pig KLHL12 (94% identical), tropical clawed frog klhl12 (93% identical), zebrafish KLHL12 (42% identical), Drosophila melanogaster kel (41% identical), Caenorhabditis elegans kel-1 (34% identical). Paralogues in human: KLHL20 (43% identical), KLHL2 (42% identical), KLHL3 (40% identical), KLHL17 (40% identical), KLHL18 (37% identical), KLHL1 (37% identical), KLHL5 (37% identical), KLHL4 (36% identical), KLHL8 (36% identical), KLHL28 (36% identical), KEAP1 (35% identical), IPP (35% identical), and 42 more.
Diseases named in the same sentence as KLHL12 in open-access papers:
KLHL12 is named in the same sentence as 10 diseases in open-access papers, as found by Europe PMC text mining. Sharing a sentence is not in itself a finding about the gene and the disease. The quoted sentences say what the papers report.
primary biliary cirrhosis (3 papers, 2022). "However, one patient with MIS-C had low levels of autoantibodies against Troponin-C2 and another patient had autoantibodies against both Troponin-C2 and the KLHL12 autoantigen associated with Sjögren’s syndrome/primary biliary cirrhosis." (PMID 35360001, 2022). "One of the two MIS-C patients had high titers of autoantibodies against Troponin C2 and against KLHL12, a known autoantigen in Sjögren’s syndrome/primary biliary cirrhosis." (PMID 35360001, 2022). "For example, KLHL12 has been identified as an autoantigen in Sjogren's syndrome and is a potential biomarker for primary biliary cirrhosis." (PMID 36684947, 2022). "In addition, 5% of patients had antibodies against KLHL12, a known autoantigen in Sjögren’s syndrome and primary biliary cirrhosis." (PMID 35360001, 2022).
liver fibrosis (2 papers, 2022 to 2025). "The level of anti-KLHL12 antibodies in sera of PBC patients is associated with the stage of liver fibrosis, which may be important in recognition of patients at risk of advanced disease or faster disease progression." (PMID 35453551, 2022). "Presence of the anti-KLHL12 antibodies in sera of PBC patients also correlated with the stage of liver fibrosis." (PMID 35453551, 2022). "Our data confirmed that there is a correlation between the presence of anti-KLHL12 antibodies, anti-nuclear envelope antibodies, liver fibrosis, and higher bilirubin concentrations in Polish PBC patients." (PMID 35453551, 2022). "The level of anti-KLHL12 antibodies in sera of PBC patients was also found to correlate with the stage of liver fibrosis." (PMID 35453551, 2022).
COVID-19 (1 paper, 2022). A disease caused by infection with severe acute respiratory syndrome coronavirus 2. "One patient had antibodies to both KLHL12 and TNNC2 which might have been due to an underlying autoimmune condition, or a predisposition to autoantibodies that was triggered by COVID-19." (PMID 35360001, 2022).
neuroblastoma (1 paper, 2025). Neuroblastoma (NB) is the most common solid, extracranial childhood tumor. "Subsequent Kaplan-Meier analysis revealed that high expression of KLHL37, rather than KLHL12 or KLHL30, was significantly associated with poor overall survival (OS) of patients with neuroblastoma." (PMID 40493396, 2025).
cancer (3 papers, 2018 to 2026). A tumor composed of atypical neoplastic, often pleomorphic cells that invade other tissues. "We have identified KLHL12 as an E3 ligase with higher expression in cancer over normal tissues." (PMID 41906311, 2026). "For many genes, their function in cancer is still unknown while some others have already been implicated in cancer such as: RABIF, KLHL12, ADIPOR1, CYBR5R1 and PRELP." (PMID 29844869, 2018). "Eight of these had decreased expression in cancer (KLHL3, KLHL4, KLHL13, KLHL14, KLHL29, KLHL30, KLHL32, and KLHL33) while four genes (ENC1, KLHL12, KLHL17, and KLHL35) had patterns of up-regulated gene expression." (PMID 30647843, 2018).
tumor (1 paper, 2025). "Moreover, we found that KLHL12 and KLHL37 had higher expression levels in tumor tissues compared with levels in adjacent tissues, whereas KLHL30 did not." (PMID 40493396, 2025).
KLHL12 also shares sentences with these, for which no sentence is quoted: Sjogren syndrome (3 papers); autoimmune disease (1); autoimmune hepatitis (1); pseudohypoaldosteronism type 2 (1).